ENSG00000253092
Synonyms: LOC124900564
Gene: Small nucleolar RNA gene on chromosome 3 (183,452,567 to 183,452,764, forward strand). Ensembl gene ENSG00000253092.
Gene Ontology:
Biological process: RNA processing
Cellular component: nucleolus
Homologues: Paralogues in human: SNORA81 (53% identical).